ENSG00000297938 (novel transcript)
Gene: Long non-coding RNA gene on chromosome 18 (48,411,202 to 48,539,013, reverse strand). Ensembl gene ENSG00000297938.
Gene Ontology:
Molecular function: structural constituent of ribosome
Cellular component: ribosome